APOE (apolipoprotein E)
Diseases named in the same sentence as APOE in open-access papers (continued):
Sharing a sentence is not in itself a finding about the gene and the disease.
atherosclerosis (continued). "Apolipoprotein E (ApoE)-deficient thrombospondin-1 knockout mice displayed increased atherosclerosis compared to Apoe−/− control mice, which the authors attributed to increased metalloproteinase activity and defective efferocytosis." (PMID 31337788, 2019). "Further suggesting an anti-inflammatory effect of thyroid hormones, additional knockout of the thyroid hormone receptor alpha in apoE knockout mice, a commonly used atherosclerosis model, increased both atherosclerotic plaque size, and plaque inflammation." (PMID 30859432, 2019). "Given that atherosclerosis is the underlying condition that causes CAD, the potential for the identified peptides to be self-reactive antigens in atherosclerosis was tested using splenocytes from 13 week-old male apoE-/- mice fed normal chow." (PMID 30811493, 2019). "These anti-inflammatory properties of APOE, combined with its impact on lipoprotein metabolism, explain why Apoe knockout mice display a very strong development of atherosclerosis compared to other mouse models." (PMID 31032262, 2019). "Previous studies demonstrated that both recombinant mice and human IL-35 attenuated atherosclerosis in ApoE-/- mice." (PMID 31093011, 2019). "In this study, we successfully established an ApoE−/− mice atherosclerosis model fed with HFD for 12 weeks." (PMID 31446617, 2019). "Among the cytokines secreted by Th1 cells, IL-18 appears to negatively regulate VSMC accumulation within atheroma lesions in ApoE−/− mice, supporting the notion that IL-18 is an important mediator of Th1-induced atherosclerosis." (PMID 31824304, 2019). "Increased interaction of various ligand-receptor pairs including Ccl2-Ccr2, Ccl7-Ccr2, and Il1b-Il1r2 between Mesen II and inflammatory cells in ApoE−/− adventitia further implied the participation of Mesen II in early development of atherosclerosis." (PMID 30943771, 2019). "Second, pharmacological inhibition of PARP-1 in atherosclerosis attenuates plaque development in ApoE-/- mice." (PMID 31019462, 2019). "At the same time, several signaling pathways that play important regulatory roles in the occurrence and development of atherosclerosis were up-regulated in ApoE−/− mice." (PMID 31446617, 2019). "In contrast, the Th2 response appears to aggravate atherosclerosis in an asthmatic ApoE−/− mouse model." (PMID 31653058, 2019). "It is reported that apoE−/− mice fed by HFD have been widely used for establishing the animal model of atherosclerosis." (PMID 31379468, 2019). "These experiments show that BH4 supplementation is capable to counteract the atherosclerosis-promoting ROS generation in Tg-B2++ApoE–/– mice with transgenic BDKRB2 expression." (PMID 30847343, 2019). "Splenectomized mice have drastically decreased levels of peritoneal B1 cells indicating that the spleen is an important provider of survival signals for B1 cells while splenectomy in apoE−/− mice leads to increased atherosclerosis." (PMID 31823769, 2019). "The ApoE−/− mice presented with features of typical atherosclerosis, such as a thin fibrous cap and the presence of foam cells and cholesterol crystals within the atherosclerotic plaque." (PMID 31886257, 2019). "We have found that trehalose, given orally for a 16-week period, was able to inhibit atherosclerosis only in the less aggressive model examined (CD-fed male apoE−/− mice)." (PMID 30925684, 2019). "For the in vivo assay, we fed ApoE knockout (KO) mice with high-fat diet for four weeks and later the potential anti-atherosclerosis effect of peach kernel oil in ApoE KO mice was evaluated." (PMID 30669336, 2019). "In the present study, we also used recombinant mouse IL-35 to treat ApoE-/- mice to further strengthen the role of IL-12p35 in atherosclerosis." (PMID 31093011, 2019).
atherosclerosis (continued). "Previous studies have shown that treatment with anti-VCAM-1 antibody inhibits leukocyte adhesion, attenuates atherosclerosis, decreases plaque inflammation, and improves plaque stability in ApoE (−/−) mice." (PMID 31300040, 2019). "NETs were also found shown in monocyte-depleted Lysmegfp/egfp atherosclerosis-prone apolipoprotein-E−/− mice within the carotid bifurcation using intravital microscopy." (PMID 31466329, 2019). "To extend our in vitro findings, we established type 2 diabetic atherosclerosis model using apoE−/− mice to explore the effect of rapamycin on CHOP expression, apoptosis and atherosclerotic lesions." (PMID 30746902, 2019). "Irisin-ApoE-/- mice showed improved hyperlipidemia and alleviated atherosclerosis as compared with ApoE-/- mice." (PMID 31191305, 2019). "For example, disruption of CD4+CD25+ Tregs with anti CD25 antibodies in ApoE−/− mice accelerates the development of atherosclerosis lesions and increases plaque vulnerability." (PMID 31653058, 2019). "Conversely, after the administration of a Western diet, atherosclerosis development in conventionally raised ApoE-/- mice was comparable to that in germ-free ApoE-/- mice." (PMID 31892152, 2019). "The apolipoprotein E knockout (ApoE -/-) mouse model is well established for the study of terpenoids in the prevention of atherosclerosis." (PMID 31392210, 2019). "To examine the beneficial effect of DCA on atherosclerosis in vivo, we established an atherosclerosis model by using ApoE−/− mice fed with a WD for 16–22 weeks." (PMID 31570705, 2019). "In conclusion, we identified the miR-106b~ 25 cluster as a novel regulator of atherosclerosis in APOE KO mice, presumably by altering plasma cholesterol levels." (PMID 31796057, 2019). "Further we examined the expression of IRF1 in atherosclerosis- prone ApoE-/- mice and normal C57BL/6 mice." (PMID 31367250, 2019). "Atherosclerosis in ApoE−/− mice is also reduced and plaques are stabilized by IL-18 blockade with an IL-18 binding protein or by genetic deletion." (PMID 31653058, 2019). "We hypothesized that atherosclerosis would be associated with endothelial dysfunction and that bosentan (Tracleer®), a dual endothelin-receptor antagonist, would preserve endothelial cell function in an apolipoprotein E-deficient (ApoE−/−) mouse model of atherosclerosis." (PMID 31886257, 2019). "Some of these common risk factors shared between CVD and AD are hypertension, diabetes, atrial fibrillation, atherosclerosis, hypercholesterolemia, and apolipoprotein E (ApoE) genotype." (PMID 31293412, 2019). "Due to the fact that the peritoneal cavity is the main residence of B1 cells we decided to transfer IL-7, IL-33-expanded ILC2s intraperitoneally to apoE−/− mice and study the induced immunological response as well as their effect on atherosclerosis." (PMID 31823769, 2019). "Over the past 20 years, studies on apolipoprotein E (apoE) and its roles in various physiologic processes (atherosclerosis, Alzheimer disease – AD, etc.)." (PMID 31623648, 2019). "They demonstrated how atherosclerosis in ApoE-/- mice correlated in a dose-dependent manner with increasing levels of dietary choline and TMAO." (PMID 31892152, 2019). "Several GPVI inhibition strategies led to reduced platelet adhesion and attenuated atherosclerosis in ApoE−/− mice." (PMID 31572732, 2019).
atherosclerosis (continued). "Consistently, the ApoE−/− mouse model in which CXCL10 or its receptor were invalidated displayed reduced atherosclerosis development." (PMID 31824304, 2019). "Exosomes derived from mesenchymal stem cells (MSCs) improved atherosclerosis in ApoE-/- mice and promoted M2 macrophage polarization in the atherosclerotic plaque by the microRNA-let7/HMGA2/NF-κB pathway." (PMID 31595163, 2019). "ApoE KO mice is one of the common animal models that has been used for atherosclerosis research in vivo." (PMID 30669336, 2019). "In ApoE-/- mice, supplementation of calcitriol was shown to attenuate atherosclerosis formation by increasing Treg subsets and decreasing differentiation of dendritic cells or by activation of VDR." (PMID 31623356, 2019). "Collectively, these data suggest that LPS exacerbates the development and progression of atherosclerosis in ApoE-/- mice, and these effects are dependent, at least partly, on IRF1 activation." (PMID 31367250, 2019). "In the present study we attempted to investigate the direct effect of the IL25-induced splenic ILC2 (Lin−CD45+IL17RB+ICOS+IL7raint) population on the development of atherosclerosis by its adoptive transfer to hypercholesterolaemic apoE−/− mice." (PMID 31823769, 2019). "Blocking HMGB1 release by EP or inhibiting TLR4 activation by TAK-242 almost reversed CUMS-induced the drownregulation of PPARγ-LXRα-ABCA1 and impeded the development of atherosclerosis in apoE-/- mice." (PMID 30881312, 2019). "As an example, when the 12/15-LOX-ApoE-/- transgenic mice were fed a Western Diet (i.e., high cholesterol, high saturated fat), atherosclerosis progression was exacerbated compared with ApoE-/- controls." (PMID 30899222, 2019). "In this study, we discovered that oral gavage of SBP markedly alleviated the development of atherosclerosis in apoE−/− mice." (PMID 31379468, 2019). "Altogether, utilization of ApoE−/− mice fed on normal laboratory diet enabled us to characterize the fine-tuned interaction between cells in the adventitia in the early stage of atherosclerosis and uncover early landscape shift of adventitial cells." (PMID 30943771, 2019). "ApoE−/− mice fed a hypercholesterolemic diet have fewer Tregs and more atherosclerosis than counterparts fed a normal diet." (PMID 31653058, 2019). "In the process of atherogenesis, GSH capacity to be synthesized in cells, but especially in macrophages, has an inverse relationship to the initiation and progression of atherosclerosis in ApoE−/− mice." (PMID 31210841, 2019). "The miR-155 levels were significantly elevated in sera from patients with atherosclerosis and in aortic vessels from ApoE−/− mice fed a HFD compared to their control counterparts, whereas the sGCβ1 protein levels were decreased in aortas from HFD-fed mice." (PMID 30765689, 2019). "CD248 is expressed in vascular smooth muscle cells (VSMCs) undergoing proliferation and remodelling in apolipoprotein‐E (ApoE) KO mouse models of atherosclerosis as well as atherosclerotic lesions from patients." (PMID 31287944, 2019). "In summary, we profiled the expression of lncRNAs and mRNAs in the aorta of an ApoE−/− mouse atherosclerosis model." (PMID 31446617, 2019).
atherosclerosis (continued). "In order to examine the effect of ginsenoside Rb1 on atherosclerosis, apolipoprotein E (ApoE)−/− mice were treated for 8 weeks at 10 mg/kg body weight." (PMID 30744138, 2019). "The ApoE -/- mouse model is well established for studying atherosclerosis, and the principal characteristics and progression of atherosclerosis in ApoE -/- mice and human subjects appear similar; however, there are differences in pathogenesis." (PMID 31392210, 2019). "Next, we explored the effect of long-term OSM administration on endothelial activation, atherosclerosis development and lesion composition in APOE*3Leiden.CETP mice, a translational model for human lipoprotein metabolism and atherosclerosis development." (PMID 31461490, 2019). "Monocyte recruitment and subsequent atherosclerosis in ApoE−/− mice are also reduced by inhibiting the chemoattractants CCL2, CXCR1, CCR5, and M-CSF, either by pharmacological blockade or genetic inactivation." (PMID 31653058, 2019). "In subanalyses stratified by number of isoprene groups, sesquiterpenoid, diterpenoid, triterpenoid, and tetraterpenoid significantly reduced aortic atherosclerosis lesion area compared to vehicle control in ApoE-/- mice." (PMID 31392210, 2019). "Blocking MCP-1, a chemokine also involved in VSMC proliferation and migration, has been demonstrated to be efficient to limit atherosclerosis progression and to increase plaque stability in the established atherosclerosis ApoE−/− mouse model." (PMID 31824304, 2019). "Protective effects of Irisin on atherosclerosis were also reported in two different ApoE-KO mouse models." (PMID 30858489, 2019). "Treatment of ApoE−/− mice with pre-miR-10a or RARα/RXRα agonists can rescue miR-10a expression to inhibit the formation of atherosclerosis." (PMID 31387590, 2019). "Statins have the potential to slow the progression of atherosclerosis through NO-mediated mechanisms, and conversely, the rate of development of atherosclerosis in Apolipoprotein E (ApoE) mice is increased when they lack eNOS." (PMID 31766595, 2019). "Taken together, the B2 bradykinin receptor mediates an enhanced production of ROS in the aorta of atherosclerosis-prone Tg-B2++ApoE–/– mice with hypercholesterolemia." (PMID 30847343, 2019). "Surprisingly, so far, in animal models of atherosclerosis (high-fat diet-fed apolipoprotein E knockout mice and high-cholesterol-fed rabbits), the action of trehalose was observed only when administered parenterally." (PMID 30925684, 2019). "In this study, we investigated the protective effects and possible mechanisms of ANP action on a high-fat diet induced early and mid-term atherosclerosis ApoE-/- mice." (PMID 32082145, 2019). "By contrast, global and liver-specific Bmal1-/- knockout and APOE-/- knockout mice show increased hyperlipidemia and atherosclerosis." (PMID 31139087, 2019). "The results showed that rIL-35 treatment inhibited Th17 immune response, upregulated Treg response, and reduced atherosclerosis in ApoE-/- mice." (PMID 31093011, 2019). "CUMS ApoE-/- mice developed more atherosclerotic lesions in aortic sinus than those in normal control ones, indicting a profound aggravation of atherosclerosis by CUMS." (PMID 30881312, 2019). "In apoE-deficient mice, deletion of CCL17 leads to delayed atherosclerosis progression and reduced numbers of macrophages and T cells in plaques suggesting a pro-atherogenic role of this cytokine." (PMID 31717832, 2019).
atherosclerosis (continued). "Both normal and model groups of mice were supplement a high-fat feeding for 8 weeks to establish the model of atherosclerosis in wild type and ApoE KO mice." (PMID 30669336, 2019). "It was further shown that injecting Nef protein into mice to achieve circulating levels reported in viremic HIV+ individuals, exacerbated dyslipidemia and development of plaque in the high fat diet ApoE−/− mouse model of atherosclerosis." (PMID 31275317, 2019). "AGEs and RAGE are increased in the atherosclerosis plaques in apoE−/− mice, whereas sRAGE treatment significantly reduces these changes." (PMID 31885827, 2019). "In this study, we aimed to investigate the effects of oral treatment with a water-based GCE on atherosclerosis and a set of CMS features that are known to increase cardiovascular risk using HFD-fed ApoE-/- mice as a model." (PMID 30818779, 2019). "PKCβ has been reported to promote vascular inflammation and exacerbate atherosclerosis in diabetic ApoE null mice." (PMID 31635287, 2019). "The angiotensin II AT1 receptor is a major contributor to atherosclerosis-promoting ROS generation in ApoE–/– mice." (PMID 30847343, 2019). "We first observe that high-salt intake promotes atherosclerosis formation in the aortas of ApoE−/− mice, through inducing the expression of NFAT5, NLRP3, and IL-1β in endothelium." (PMID 31429763, 2019). "The apolipoprotein E knockout (ApoE -/-) mouse model spontaneously develops atherosclerotic plaques and is commonly used to mimic the pathophysiological process of atherosclerosis in humans." (PMID 31392210, 2019). "ApoE knock-out mice (ApoE−/−) are proposed as a model of atherosclerosis and endothelial dysfunction." (PMID 31578395, 2019). "Genetic ablation of CypA in ApoE KO mice has been shown to be anti-atherogenic, whereas pharmacological inhibition of CypA in ApoE KO mice promotes atherosclerosis." (PMID 31877775, 2019). "For in vivo studies, Ang II-infused, atherosclerosis-prone apolipoprotein E knockout mice were utilized." (PMID 31562296, 2019). "To validate the prosenescent and proatherogenic properties of electronegative VLDL and LDL in vivo, we conducted experiments with ApoE−/− mice, an atherosclerosis-prone animal model." (PMID 31404961, 2019). "In this study we show that treatment with the FXa inhibitor rivaroxaban not only decreases the onset and progression of atherosclerosis but also induces regression of already developed atherosclerotic lesions in ApoE−/− mice." (PMID 30846818, 2019). "We further found that uremia accelerated the progression of atherosclerosis in ApoE−/− mice and exogenous H2S can inhibit the progression of atherosclerosis in uremia ApoE−/− mice." (PMID 31521120, 2019). "8-week-old male ApoE−/− mice were treated with 5/6 nephrectomy and high-fat diet to make uremia accelerated atherosclerosis (UAAS) model." (PMID 31521120, 2019). "We identified the miR-106b~ 25 cluster as a novel regulator of atherosclerosis in ApoE KO mice, presumably by regulating plasma cholesterol levels." (PMID 31796057, 2019). "These APOE knockout rats demonstrated a specific feature of atherosclerosis such as adventitial immune infiltrates." (PMID 31086658, 2019).